ZEB2 (zinc finger E-box binding homeobox 2)
Description:
Transcriptional inhibitor that binds to DNA sequence 5'-CACCT-3' in different promoters. Represses transcription of E-cadherin. Represses expression of MEOX2.
Synonyms: SMADIP1; KIAA0569; SIP1; ZFHX1B; SIP-1; HSPC082
Tractability: Antibody: its Gene Ontology location is reachable by antibodies, with high confidence. PROTAC: UniProt records ubiquitination sites on it; ubiquitination databases record sites on it; its protein half-life has been measured.
Gene: Protein-coding gene on chromosome 2 (144,364,364 to 144,521,057, reverse strand). Ensembl gene ENSG00000169554.
Subcellular location: Nucleus; Chromosome
Subcellular location (Human Protein Atlas): Nucleoli; Nucleoplasm; Plasma membrane
Pathways (Reactome):
Cell-Cell communication: Negative Regulation of CDH1 Gene Transcription; Positive Regulation of CDH1 Gene Transcription; Regulation of CDH11 gene transcription
Developmental Biology: Formation of the anterior neural plate; Formation of the posterior neural plate
Gene Ontology:
Molecular function: DNA-binding transcription repressor activity, RNA polymerase II-specific; protein binding; RNA polymerase II cis-regulatory region sequence-specific DNA binding; DNA-binding transcription factor activity, RNA polymerase II-specific; phosphatase regulator activity; DNA binding
Biological process: negative regulation of transcription by RNA polymerase II; positive regulation of canonical Wnt signaling pathway; positive regulation of transcription by RNA polymerase II; positive regulation of transforming growth factor beta receptor signaling pathway; central nervous system development; developmental pigmentation; melanocyte migration; nervous system development; positive regulation of melanin biosynthetic process; positive regulation of melanocyte differentiation; regulation of melanosome organization; regulation of transcription by RNA polymerase II; positive regulation of Wnt signaling pathway
Cellular component: chromatin; chromosome; nucleolus; nucleoplasm; nucleus
Genetic constraint (gnomAD): Loss-of-function variants: 6 observed, 104.14 expected, observed/expected ratio (o/e) 0.0576, 90% interval 0.031 to 0.11. The upper end of that interval is the gene's LOEUF score, 0.11, which puts it in group 1 of 6, group 1 being the genes least tolerant of losing a copy. Missense variants: 969 observed, 1,583 expected, observed/expected ratio (o/e) 0.61, 90% interval 0.58 to 0.64. Synonymous variants: 517 observed, 571.66 expected, observed/expected ratio (o/e) 0.9, 90% interval 0.84 to 0.97.
Gene-disease validity (ClinGen):
ClinGen rates the evidence that ZEB2 causes each of these diseases.
Mowat-Wilson syndrome (autosomal dominant): Definitive. Mowat-Wilson syndrome (MWS) is a multiple congenital anomaly syndrome characterized by a distinct facial phenotype, intellectual disability, epilepsy, Hirschsprung disease (HSCR) and variable congenital malformations.
Homologues: Orthologues: chimpanzee ZEB2 (99% identical), macaque ZEB2 (99% identical), guinea pig ZEB2 (98% identical), rat Zeb2 (97% identical), dog ZEB2 (97% identical), mouse Zeb2 (97% identical), rabbit ZEB2 (96% identical), tropical clawed frog zeb2 (87% identical), zebrafish zeb2b (72% identical). Paralogues in human: ZEB1 (42% identical).
Diseases named in the same sentence as ZEB2 in open-access papers:
ZEB2 is named in the same sentence as 274 diseases in open-access papers, as found by Europe PMC text mining. Sharing a sentence is not in itself a finding about the gene and the disease. The quoted sentences say what the papers report.
breast carcinoma (197 papers, 2009 to 2026). "ZEB2, a transcription factor, is associated with drug resistance in breast cancer cells through its regulation of the epithelial–mesenchymal transition (EMT)." (PMID 41375077, 2025). "A few studies have implicated a prognostic role for ZEB1 and ZEB2 in tumor types such as ovarian, colorectal, and breast carcinomas." (PMID 38719798, 2024). "Our result is supported by research by Lin, which showed that ZEB1 and ZEB2 mRNA expression as well as protein expression were associated with poor survival in breast cancer." (PMID 30976202, 2019). "Recently, our group demonstrated that epithelial-mesenchymal transition (EMT)-associated transcription factors ZEB1 and ZEB2 are potential targets for the regulation of self-renewal and tumorigenicity of canine mammary cancer cells." (PMID 31758045, 2019). "Control of oncogenes, including ZEB1 and ZEB2, is a major checkpoint for preventing cancer, and loss of this control contributes to many cancers, including breast cancer." (PMID 29963231, 2018). "The expression of EMT markers, including CDH1, CDH2, VIM, ZEB1 and ZEB2, is associated with poor prognosis of breast cancer patients." (PMID 26062653, 2015). "In addition, we also provide evidence that overexpression of ZEB2 or ACSL4 is associated with worse prognosis in advanced breast cancer." (PMID 38078907, 2023). "Similarly, aberrant expression of TG2 in breast cancer (BC) was associated with loss of E-cadherin and upregulation of the transcriptional repressors, Snail1, Zeb1, Zeb2 and Twist1." (PMID 35681474, 2022). "However, the association between circRNA and ZEB2 in the pathogenesis of breast cancer is still unclear." (PMID 30979827, 2019). "Additionally, the expression of HIF-2α (EPAS1) is associated with ZEB2-induced EMT in breast cancer." (PMID 29164272, 2018). "Overexpression of ZEB1 and ZEB2 is a common phenomenon in many types of cancer, where it is associated with the maintenance of a cancer stem cell phenotype as well as metastasis and therapy resistance, such as paclitaxel resistance in breast cancer cells." (PMID 29164272, 2018). "However, the observations that ZEB2 introns are transcribed in modular patterns, potentially generating many ncRNAs, and that such intronic transcripts are strongly associated with breast cancer add a new direction to the analysis of the ZEB2 locus." (PMID 25798919, 2015). "Results of recent studies have shown that ZEB1 and ZEB2 are associate with the response to radiotherapy and chemotherapy of several cancers, such as pancreatic carcinoma, head and neck squamous carcinoma, squamous carcinoma, breast cancer, non-small cell lung, and bladder carcinoma." (PMID 37636389, 2023). "UBD was reported to enhances breast cancer metastasis by stabilizing ZEB2 and facilitating the EMT process." (PMID 41583390, 2026). "As a potent inducer of EMT, the role of ZEB2 has been elaborated in various cancers, such as breast carcinoma, colorectal carcinoma, gynecologic carcinoma, and lymphoblastic/myeloblastic leukemia." (PMID 40510028, 2025). "ThPOK-kd led to an increase in the expression of EMT factors (VIM, SNAI2, ZEB1, ZEB2), basal markers and WNT/β-catenin target genes implicated in breast cancer cell proliferation." (PMID 41231242, 2025). "ZEB1 and ZEB2 have been experimentally shown to promote cell migration and invasion in breast cancer and pancreatic cancer." (PMID 40830747, 2025). "For example, in breast cancer, the restoration of miR-200c expression has been shown to significantly inhibit cell migration and invasion by targeting and downregulating ZEB2, a key player in promoting EMT." (PMID 39859424, 2025).
breast carcinoma (continued). "This agrees with data in breast cancer identifying ZEB2 as being important for tumor cell migration and invasion and ZEB1 being more important for tumor cell growth/colony formation." (PMID 40736379, 2025). "SLCO1B3 acts as a tumor suppressor by inhibiting the development and progression of breast cancer, while ZEB2 promotes the growth and metastasis of liver cancer." (PMID 41187171, 2025). "Aberrant expression of adhesion and invasion proteins, including MMPs, CD44, N-cadherin, and ZEB-2, are key signs of breast cancer progression and metastasis; they represent relevant molecular targets." (PMID 40940940, 2025). "Teniposide treatment of breast cancer cells yielded high NMI/ZEB2 expression that correlated with a dramatic shift in their EMT phenotype." (PMID 38719798, 2024). "Our survey of TCGA breast cancer patient data for ZEB2 further highlights the importance of ZEB2 in predicting patient survival." (PMID 38719798, 2024). "Kaplan–Meier survival analysis showed that breast cancer patients with low ratio of NMI/ZEB2 (NMI/ZEB2 Lo) had significantly worse (p = 0.02) relapse-free survival compared to patients with a higher ratio." (PMID 38719798, 2024). "Teniposide reduced ZEB2 levels leading to downregulated rDNA transcription and mesenchymal attributes of breast cancer cells." (PMID 38719798, 2024). "A few studies have implicated a prognostic role for EMT-related transcription factors ZEB1 and ZEB2 in tumor types, such as ovarian, colorectal, and breast carcinomas." (PMID 38719798, 2024). "Our findings provide evidence for the combined role of ZEB1 and ZEB2 in the acquisition of the EMT phenotype in primary breast cancer." (PMID 39256881, 2024). "Limited studies of ZEB2 are available in breast cancer patient cohorts, with one study identifying increased ZEB2 in triple-negative breast cancer as a prognostic indicator for poor survival." (PMID 38719798, 2024). "by using the TCGA database, we compared the overall survival between ACSL4 or ZEB2 high- and low-expression breast cancer patients." (PMID 38078907, 2023). "(B) The correlation between ACSL4 and ZEB2 mRNA expression in the TCGA cohort consisting of 1222 breast cancer patient samples." (PMID 38078907, 2023). "Zeb2 has also been pointed out as possible hybrid-EMT marker in breast cancer, as its mRNA is highly expressed in cells with hybrid E/M and Mesenchymal phenotypes." (PMID 36797240, 2023). "(E) OS (overall-progression survival) as examined by Kaplan–Meier analysis to compare the survival rates in ZEB2 high and low expression of breast cancer patients." (PMID 38078907, 2023). "Survival analysis revealed that breast cancer patients with high expression of both ACSL4 and ZEB2 are associated with worse overall survival than those patients with low expression." (PMID 38078907, 2023). "For example, lincRoR has been found to act as a competing endogenous RNA of microRNA-205, which prevented the degradation of EMT inducer ZEB2 and enhanced the aggressiveness of breast cancer cells." (PMID 36986051, 2023). "Previous study has indicated that UBD (FAT10/Ubiquitin D) promotes the invasion of the progressive breast cancer cell by stabilizing ZEB2." (PMID 37475016, 2023). "(J) HE staining and IHC analysis of ACSL4, ZEB2, ERɑ expression in representative basal-like and luminal subtype breast cancer tissues." (PMID 38078907, 2023). "ACSL4 and ZEB2 increase fatty acid oxygen consumption and promote adenosine triphosphate (ATP) generation in basal-like breast cancer (BLBC) cells." (PMID 38078907, 2023). "Consistently, tissue samples from 45 breast cancer patients had similar expression patterns, with ZEB2 and ACSL4 being relatively highly expressed in ER-negative patient samples (patients 6, 7, 8, and 9)." (PMID 38078907, 2023). "Although one study examined the expression of ZEB1 and ZEB2 in five canine mammary carcinoma cell lines, to the best of our knowledge, ZEB mRNA expression has never been studied in CMT and FMT tissues." (PMID 36899736, 2023).
breast carcinoma (continued). "(G) Expression of ACSL4 and ZEB2 was analyzed by western blot in a panel of five breast cancer cell lines, including two basal-like (MAD-231, BT549), two luminal (T47D, MCF-7), and a Taxol-resistant cell lines." (PMID 38078907, 2023). "Taken together, these results indicate that ACSL4 and ZEB2 are correlated and overexpressed in highly invasive breast cancers." (PMID 38078907, 2023). "Cluster 5 is enriched in lung carcinoma and breast cancer samples with a general high activity of ZEB2, a promoter of epithelial to mesenchymal transition (EMT), metastasis and resistance in LUAD and breast cancer." (PMID 36688815, 2023). "(H) The correlation between ACSL4 and ZEB2 protein expression in the immunohistochemistry (IHC) cohort consisting of 45 breast cancer patient samples." (PMID 38078907, 2023). "In another breast cancer research, FOXA1 was found to downregulate EMT-associated markers, including E-cadherin, ZEB2, and vimentin, eventually preventing EMT progression." (PMID 36393971, 2022). "ZEB2 is reported to be an oncogene in multiple malignancies, including liver cancer, breast cancer, colorectal cancer, esophageal squamous cell carcinoma, and NSCLC." (PMID 34839824, 2021). "Our previous research found that FOXA2 inhibits EMT in breast cancer cells by stimulating E-cadherin transcription and repressing ZEB2 transcription." (PMID 33718155, 2021). "To further confirm this functional link, we investigated the influence of CUL4B, MTA1, Snail, and ZEB2 on the cellular behavior of breast cancer cells in vitro using transwell invasion assays." (PMID 34026424, 2021). "From the perspective of translational application, ZEB2 has been reported as an adverse prognostic marker in some tumours, such as breast cancer, bladder carcinoma and glioma." (PMID 34211089, 2021). "Reportedly, zinc finger E-box binding homeobox 2 (ZEB2) is a target of miR-124 in breast cancer, and reduction of ZEB2 suppresses EMT and metastasis." (PMID 34072894, 2021). "In breast cancer, miR-338-3p can negatively regulate ZEB2 to repress cell growth, migration, invasion and epithelial–mesenchymal transition (EMT)." (PMID 34889689, 2021). "Current study has shown that OIP5-AS1 was up-regulated in breast cancer which regulates the expression of ZEB2 by acting as competitive endogenous RNA (ceRNA) for miR-340-5p, and then promotes metastasis of breast cancer." (PMID 34345216, 2021). "ΔNp63 has also been linked to selective regulation of EMT factors in breast cancer cells, as upregulation of SNAI2 lead to increased migration while miR-205 mediated inhibition of ZEB1 and ZEB2 resulted in EMT suppression." (PMID 34964086, 2021). "For example, silencing of has_circ_0004771 inhibits proliferation and induces apoptosis in breast cancer through activation of miR-653 by targeting ZEB2 signaling pathway." (PMID 34900700, 2021). "A team of scientists led by Lee73 showed that miR-205 inhibits both Zeb1 and Zeb2 mRNAs in the breast cancer cell lines MCF7, MDA231, and SK-BR-3." (PMID 33414456, 2021). "For example, the overexpression of miR-21 in MCF7 cells will promote growth and invasion ability of cells; miR-200 family can target ZEB1 and ZEB2 genes to inhibit breast cancer cells." (PMID 33428601, 2021). "Secondly, CdGAP was shown to translocate to the nucleus and form a functional complex with the transcriptional factor ZEB2 to repress E-cadherin expression in breast cancer cells." (PMID 34493786, 2021). "Further, miR-200-overexpressing mouse breast cancer cell lines surprisingly exhibit lung and liver macroscopic metastases via reduced ZEB2 and elevated E-cadherin expression inducing MET." (PMID 32708601, 2020). "In fact, MiR-200c regulates EMT by inhibiting ZEB1 and ZEB2 expression in breast cancer cells, while it regulates CSCs heterogeneity via targeting the HIPK1/β-Catenin axis." (PMID 33092068, 2020).
breast carcinoma (continued). "PGI/AMF induced Epithelial-Mesenchymal Transition (EMT), increasing the expression of ZEB1/ZEB2 (mesenchymal markers; Zinc finger E-Box-binding homeobox 1/Zinc finger E-Box-binding homeobox 2) through the Nuclear Factor-kB (NF-kB) in breast cancer cells." (PMID 31952362, 2020). "Up-regulated H3K79 methylation on the SNAIL, ZEB1 and ZEB2 promoters enhances EMT-induced breast-cancer invasion and metastasis." (PMID 32042335, 2020). "In breast cancers, YB‐1 translationally controls the epithelial‐to‐mesenchymal transition (EMT) by activating expression of transcription factors such as SNAIL, TWIST, and ZEB2 to drive breast cancer EMT and metastasis." (PMID 31668005, 2019). "Knockdown of hsa_circ_0004771 and ZEB2 served as equally authentic of miR-653 mimics to induce growth inhibition and apoptosis in breast cancer cells." (PMID 30979827, 2019). "Knockdown of hsa_circ_0004771 and ZEB2 served as the equally authentic of miR-653 mimics to induce growth inhibition and apoptosis in breast cancer cells." (PMID 30979827, 2019). "Previous studies also uncover that ZEB2 can be regulated by miRNAs, including miR-29b, miR-30a, miR-155, miR-204 and miR-205, in the development of breast cancer aggressiveness." (PMID 30979827, 2019). "In the present study, our findings extended the role of ZEB2, as an oncogene promotion of cell proliferation in breast cancer, that was a direct target of miR-653." (PMID 30979827, 2019). "Numerous studies also reveal that ZEB2 contributes to breast cancer progression by coordinating EMT." (PMID 30979827, 2019). "In vitro experiments uncovered that hsa_circ_0004771/miR-653/ZEB2 axis was involved in breast cancer cells proliferation and apoptosis." (PMID 30979827, 2019). "We also found that hsa_circ_0004771 performed a parallel effect to ZEB2 and an opposite effect to miR-653 in breast cancer cell proliferation and apoptosis." (PMID 30979827, 2019). "Here, we report that the Rho GTPase activators Vav2 and Vav3 utilize a new Rac1-dependent and miR-200c-dependent mechanism that maintains the epithelial state by limiting the abundance of the Zeb2 transcriptional repressor in breast cancer cells." (PMID 30087437, 2019). "In collection, these findings indicated that hsa_circ_0004771/miR-653/ZEB2 signaling pathway provided a new perspective for the treatment of breast cancer." (PMID 30979827, 2019). "More importantly, hsa_circ_0004771/miR-653/ZEB2 aixs contributed to the development of the new therapeutic targets for the treatment of breast cancer." (PMID 30979827, 2019). "Post-transcriptional regulatory mechanism has been shown that miR-30a, miR-155 and miR-200 family members inhibit human breast cancer cells invasion by down-regulating ZEB2." (PMID 30979827, 2019). "We then examined the consequences of the regulation of ZEB2 by FOXP3 and miR-155 on sentinel marker genes implicated in the invasive and migratory potential of human breast cancer cells." (PMID 29963231, 2018). "In breast cancer cells repression of ZEB2, independently of ZEB1, resulted in reduced expression of a mesenchymal marker, Vimentin and reduced invasion." (PMID 29963231, 2018). "We confirmed this knowledge by querying the expression of ZEB1 (and its related transcription factor ZEB2) in several human breast cancer cell lines based on data available in the GOBO database." (PMID 29744893, 2018). "Expression of ZEB2 is much higher in the aggressive breast cancer cell lines BT549 and MDA-MB-231, compared with its expression in normal human mammary breast epithelia (HMEC)." (PMID 29963231, 2018). "Knocking-down ZEB2 (ZEB2-KD) in the mesenchymal-like MDA-MB-231 breast cancer cell line (which expresses more endogenous ZEB2 and less RAB25 than MCF7 cells) induced the expression of RAB25 and CDH1." (PMID 30445998, 2018).